TRAP1 (TNF receptor associated protein 1)
Diseases named in the same sentence as TRAP1 in open-access papers (continued):
Sharing a sentence is not in itself a finding about the gene and the disease.
ovarian carcinoma (24 papers, 2012 to 2025). A malignant neoplasm originating from the surface ovarian epithelium. "Conversely, low TRAP1 expression was linked to cisplatin resistance in ovarian cancer cells and poor outcomes in cervical, bladder, and clear renal cell carcinoma." (PMID 37508418, 2023). "drugs indicates that kidney and ovarian cancer subtypes are clustered together and display the strongest and most significant associations between high TRAP1 expression and sensitivity to DNA rep." (PMID 37508418, 2023). "In ovarian cancer cell lines, high TRAP1 expression was significantly associated with sensitivity to 54% of DNA rep." (PMID 37508418, 2023). "A similar observation was previously obtained by our group in human ovarian carcinoma, a malignancy characterized by TRAP1 downregulation with parallel loss of its gene CN across tumor stage and development of platinum resistance." (PMID 31878280, 2019). "We showed that TRAP1 expression is inversely correlated with tumor stage and grade and is directly associated to better survival in a large datasets of ovarian cancer patients." (PMID 29621137, 2018). "In this tumor, the TRAP1 gene is deleted in the late stages of the disease, suggesting genetic loss as the most likely mechanism for the decrease in TRAP1 expression as ovarian cancer progresses." (PMID 29621137, 2018). "The role of the tumor necrosis factor receptor associated protein 1 (TRAP1) – supposed to be involved in protection of cells from apoptosis and oxidative stress – has just started to be investigated in ovarian cancer." (PMID 22978347, 2012). "The results reported herein partially solve present controversies on TRAP1 functions in the regulation of energetic metabolism, and provide novel elements to shed light on new molecular mechanisms underlying this control, as well as novel targets to be explored for ovarian cancer therapy." (PMID 36510251, 2022). "Next, we isolated mitochondria from two ovarian cancer cells and found that mitochondrial proteases (Clpp and Lonp) and molecular chaperones (Hsp60 and Trap1) increased in A2780 cells compared to SKOV3 cells." (PMID 38238825, 2024). "Matassa and colleagues have similarly suggested the involvement of the oxidative phosphorylation pathway in ovarian cancer cell resistance, possibly mediated through TRAP1." (PMID 38461424, 2024). "Among the 12 downregulated genes (FC range from −1.5 to −2.9) was TRAP1, a member of the HSP90 protein family, which is associated with induction of EMT in ovarian cancer." (PMID 36968142, 2023). "As ovarian cancer progresses, the expression of TRAP1 decreases, the cellular metabolic characteristics shift to OXPHOS, and both the invasion and cisplatin resistance of the cancer cells increase." (PMID 33575209, 2020). "We previously observed that metabolic rewiring toward mitochondrial respiration drives resistance to 5‐fluorouracil (FU) in FU‐resistant CRC cells and to platinum in ovarian carcinoma cells upon TRAP1 downregulation." (PMID 33025742, 2020). "Up to now, TRAP-1 has been mainly considered as an oncogenic protein in many cancers (prostate, colorectal and breast cancers) but recently some evidences are in favor of the tumor suppressor role of TRAP-1 in some cancers as in ovarian cancer." (PMID 35582577, 2019). "Tumor necrosis factor receptor-associated protein 1 (TRAP1), the mitochondrial homologue of HSP90, is significantly involved in several cancers including ovarian cancer." (PMID 31540420, 2019). "Of note, recent insights on ovarian cancer assign TRAP1 a key metabolic role in disease progression, platinum response and inflammatory activation." (PMID 31540420, 2019). "It has been demonstrated that treatment of ovarian cancer cells induced HSP27, HSP70 and HSP90 as well as HSP60 and TNF receptor-associated protein 1 (TRAP-1) and the use of HSP inhibitors was shown to be active against the growth of resistant tumors." (PMID 35582577, 2019).
ovarian carcinoma (continued). "Certain HSP90 isoforms such as TRAP1 can modulate the responsiveness to anti-cancer drugs such as cisplatin in ovarian cancer." (PMID 31540420, 2019). "This puzzling function of TRAP1 in ovarian cancer fits well with the demonstration of TRAP1 being responsible for, or involved in, the shift of glycolytic metabolism toward oxidative phosphorylation." (PMID 29621137, 2018). "TRAP1 expression was also inversely correlated to the expression of several markers of epithelial-mesenchymal transition in both ovarian cancer cells and tissues." (PMID 29621137, 2018). "Microarray analysis of expression changes in human ERα-positive ovarian cancer cell lines upon 17ß-estradiol stimulation, identified TRAP1 to be estrogen up-regulated and to be involved in growth regulation of EOC." (PMID 22978347, 2012). "Expressions of TRAP1 and ERα were evaluated by immunohistochemical staining of tissue microarrays comprised of 208 ovarian cancer samples." (PMID 22978347, 2012). "Up to now, only one study has addressed TRAP1 protein expression in human ovarian cancer tissue in regard to therapy response." (PMID 22978347, 2012). "Initially, expression of the molecular chaperone TRAP1 in human ovarian cancer was determined by immunohistochemistry." (PMID 22978347, 2012). "In breast cancer cells, HSPs influence tumorigenesis and in ovarian cancer, TRAP1 has recently been questioned as a new potential molecular target." (PMID 22978347, 2012). "TRAP1 has been shown to be estrogen up-regulated in estrogen receptor α (ERα) positive ovarian cancer cells." (PMID 22978347, 2012). "We have evaluated the expression of ERα in EOC together with the expression of TRAP1, that has been described to be up-regulated in vitro in ER positive ovarian cancer cells exposed to estrogen." (PMID 22978347, 2012). "Ovarian cancer tissues expressing ERα were more likely to show high TRAP1 expression levels (67.0%, p < 0.001)." (PMID 22978347, 2012). "In the case of TRAP1, the majority of human malignancies are characterized by its upregulation (i.e., colorectal, lung, breast and prostate carcinomas), whereas selected tumors by its downregulation (i.e., renal, cervical and ovarian carcinomas)." (PMID 31878280, 2019). "Interestingly, recent data from large scale studies demonstrated that lower TRAP1 levels that have been surprisingly observed in ovarian cancer are compatible with bad prognosis." (PMID 31540420, 2019). "In ovarian cancer where TRAP1 expression was altered, metformin was effective in rendering the tumor sensitive to chemotherapy, suggesting that metformin might be relevant to TRAP1 mediated signaling." (PMID 30072954, 2018). "The hypothesis that TRAP1 may act as a tumor suppressor depending on the tumor type and its relative context was initially suggested by a study of 208 patients affected by ovarian cancer." (PMID 29621137, 2018). "Combined, these data suggest a novel role for TRAP1 and oxidative metabolism in cancer progression and candidate targeting of mitochondrial bioenergetics as a strategy to improve cisplatin activity in human ovarian cancer." (PMID 29621137, 2018). "Consequently, the anti-oxidant activity of TRAP1 could hamper growth in specific tumor types or stages as in cervical carcinoma, clear cell renal cell carcinoma and high-grade ovarian cancer, where TRAP1 expression inversely correlates with tumor grade." (PMID 32766157, 2020). "Since previous data in human ovarian carcinoma suggest that TRAP1 expression is dependent on genetic alterations regarding its gene copy number the hypothesis that TRAP1 modulation in human CRC depends on transcriptional mechanisms was evaluated by analyzing the TCGA database." (PMID 28177905, 2017).
ovarian carcinoma (continued). "However, high TRAP1 levels were also found in 42% of ER negative tumors, revealing two independent but interconnected parameters i) ERα, described to play a dominant role in ovarian cancer and ii) TRAP1, a mitochondrial chaperone, selectively up-regulated in tumor cells and up-regulated by estrogen." (PMID 22978347, 2012). "Low expression of TRAP1 was found to induce upregulation of MMP2 and MMP9 mRNAs expression in ovarian cancer cells, thus triggering EMT." (PMID 33575209, 2020). "This study provides evidence for further molecular mechanisms involved in TRAP1-dependent regulation of cancer cell metabolism, and points out complex III components and activity as a potential novel target for metabolic therapy, especially in ovarian cancer." (PMID 36510251, 2022). "On the contrary, in other investigations performed on human ovarian cancer, TRAP1 downregulation resulted in the enhancement of invasion and EMT; such a discrepancy implies that cancer stemness-related activities of TRAP1 may cardinally differ in various types of tumors." (PMID 32268506, 2020).
breast carcinoma (19 papers, 2012 to 2023). "A similar, but not identical, in vivo consequence of TRAP1 loss was reported in a TRAP1-deficient mouse model of breast cancer." (PMID 35883436, 2022). "By monitoring mitochondrial aerobic respiratory in real time, we provide direct evidences here that TRAP1 is required for the oxidative phosphorylation of breast cancer cells, under both normal and nutrient-deficient conditions." (PMID 26517089, 2015). "Interestingly, the expression of TRAP1 in human breast cancer samples is inversely associated with tumour grade." (PMID 31052256, 2019). "Relatively lower TRAP1 levels are associated with the rod-shaped mitochondrial phenotype in invasive and metastatic MDA-MB-231 breast cancer cells; on the contrary, higher TRAP1 levels are associated with the tubular network-shaped mitochondrial phenotype in non-invasive MCF-7 cells." (PMID 26517089, 2015). "Additionally, TRAP1 (TNF receptor associated protein 1), a molecular chaperone involved in the regulation of energetic metabolism in several cancers including breast cancer, was significantly downregulated after treatment with Vermentino extract, in accordance with the proteomic results." (PMID 32244364, 2020). "Instead, TRAP1 modulates mitochondrial dynamics and function, and links these processes to the tumorigenesis of breast cancer." (PMID 38098505, 2023). "In summary, our results indicated that although gene expression levels of HSP90AA1, HSP90AA2, HSP90AB1, HSP90B1, and TRAP1 were upregulated in breast cancer patients, only the expression of HSP90AA1 was related to the tumor stage and prognostic survival." (PMID 34109171, 2021). "In this study, we investigated the expression patterns and prognostic values of different HSP90 family members (HSP90AA1, HSP90AA2, HSP90AB1, HSP90B1, and TRAP1) in breast cancer." (PMID 34109171, 2021). "Although the mRNA levels of HSP90AB1, HSP90B1, and TRAP1 were increased in breast cancer tissues compared with those in normal tissues, the mRNA levels were not significant." (PMID 34109171, 2021). "In such a context, TRAP1 is upregulated in drug-resistant colon cancer cells and in paclitaxel- and doxorubicin-resistant breast carcinoma cells." (PMID 31947673, 2020). "We therefore confirmed the existence and inducibility of the TRAP1 complex in four other cell lines: breast cancer-derived cell lines MCF-7 and MDA-MB-134, the prostate cancer cell line PC3, and the colon cancer cell line HCT116." (PMID 31987035, 2020). "This evidence suggests a possible TRAP1 involvement in the development of therapeutic strategies targeting breast cancer." (PMID 31052256, 2019). "Hsp90AA1, Hsp90AB1, TRAP1, HspA5, HspB1, HspE1, HspD1, HspA1B, HspA8, HspA9, and HspA4 were validated as potential biomarkers for breast cancer tissue." (PMID 31921692, 2019). "TRAP1 can be upregulated in human breast carcinomas, and this upregulation is correlated with endoplasmic reticulum stress." (PMID 31052256, 2019). "Multiple heat shock proteins, including Hsp90AA1, Hsp90AB1, TRAP1, HspA5, HspB1, HspE1, HspD1, HspA1B, HspA8, HspA9, and HspA4, were significantly upregulated in breast cancer tissue." (PMID 31921692, 2019). "Heat shock proteins showed the most significant change of all the upregulated domains, with Hsp90AA1, Hsp90AB1, TRAP1, HspA5, HspB1, HspE1, HspD1, HspA1B, HspA8, HspA9, and HspA4 identified in breast cancer tissue." (PMID 31921692, 2019). "It is well known that different molecular chaperones are overexpressed in breast cancer, i.e., Hsp90 and its mitochondrial homologues TRAP1, Hsp70, and Hsp27." (PMID 30781465, 2019). "Conversely, in two different breast cancer cell lines, stable knockdown of TRAP1 via short hairpin RNA (shRNA) was responsible for a decrease in OCR." (PMID 29621137, 2018). "TRAP1 knockdown in breast cancer cells also sensitized cells to lethal stimuli and inhibited tumor growth." (PMID 29621137, 2018).
breast carcinoma (continued). "In previously reported xenograft assays performed with SAOS-2 osteosarcoma cells, MDA-MB-231 and MCF-7 breast cancer cells, and human esophageal cancer cells, knocking down Trap1 by RNA interference resulted in decreased tumor growth." (PMID 28407697, 2017). "We aimed to address the issue of Hsp90α and Trap1 involvement specifically in breast cancer initiation, progression and metastasis by using an in vivo mouse breast cancer model." (PMID 28407697, 2017). "To obtain initial correlative evidence for the potential role of Hsp90α and Trap1 in the tumorigenic and metastatic processes in the PyMT breast cancer model, we checked their protein levels in normal and cancer tissues." (PMID 28407697, 2017). "Using a breast cancer xenograft model, a recent study showed decreased tumorigenesis when Trap1 expression was knocked down, whereas overexpression of Trap1 resulted in decreased metastasis." (PMID 28407697, 2017). "We also manipulated TRAP1 levels in different types of breast cancer cells and measured its effect on tumorigenesis and metastasis in vitro and in vivo." (PMID 26517089, 2015). "Given the fact that TRAP1 is overexpressed in breast cancer and is crucial for tumorigenesis, we examined TRAP1 protein levels in different human breast cancer specimens by immunohistochemical staining." (PMID 26517089, 2015). "In this study, we analyzed the expression of TRAP1 in breast tumor specimens and established breast cancer cell lines by Western blot and immunohistochemistry." (PMID 26517089, 2015). "TRAP1 is generally crucial for colony formation and tumor growth of the breast cancer cells we tested; however, the cellular responses after TRAP1 knockdown were different." (PMID 26517089, 2015). "Since late-grade tumors (Grade 3 and 4) often have a higher metastatic capacity, we next analyzed TRAP1 levels in breast cancer cell lines with different invasive and metastatic abilities." (PMID 26517089, 2015). "Based on the results, we propose that TRAP1 exhibits essential roles in tumorigenesis of breast cancer via modulation of mitochondrial homeostasis." (PMID 26517089, 2015). "We also provided direct evidence that TRAP1 links mitochondrial morphology and function with tumorigenesis in breast cancer cells." (PMID 26517089, 2015). "In conclusion, the mitochondrial chaperone TRAP1 is overexpressed in breast cancer and is required for tumorigenesis and progression, and contributes to the adaptation to unfavorable stress conditions by regulating mitochondrial homeostasis." (PMID 26517089, 2015). "TRAP1 expression inversely correlates with tumor grade in breast cancers; moreover, levels of TRAP1 were lower in invasive breast cancer cell lines than in non-invasive cell lines." (PMID 26517089, 2015). "Metastatic MDA-MB-231 breast cancer cells express relatively low level of TRAP1, and their mitochondria were more fragmented (rod-shaped)." (PMID 26517089, 2015). "An Aberrant upregulation of TRAP1 has been reported in the tumorigenesis of breast cancer." (PMID 38098505, 2023). "Indeed, TRAP1 deletion delayed tumor formation in a mouse model of breast cancer, providing direct evidence of the role of TRAP1 in tumor initiation." (PMID 35740911, 2022). "Therefore, TRAP1 modulates mitochondrial dynamics and function, and links these processes to the tumorigenesis of breast cancer." (PMID 31052256, 2019). "Moreover, TRAP1 upregulation in breast cancer cells led to paclitaxel resistance, a drug commonly used in breast cancer treatment that alters microtubule assembly and induces endoplasmic reticulum (ER) stress and to genotoxic agents, such as anthracyclins." (PMID 29621137, 2018). "In contrast, the results obtained for Trap1 require further investigations to clarify exactly which human breast cancer type may be represented by the mouse model with respect to Trap1." (PMID 28407697, 2017). "Here we report the effects of deleting the Hsp90a or Trap1 genes in a mouse model of breast cancer." (PMID 28407697, 2017).